XBP1 (X-box binding protein 1)
Description:
Functions as a transcription factor during endoplasmic reticulum (ER) stress by regulating the unfolded protein response (UPR). Required for cardiac myogenesis and hepatogenesis during embryonic development, and the development of secretory tissues such as exocrine pancreas and salivary gland (By similarity). Involved in terminal differentiation of B lymphocytes to plasma cells and production of immunoglobulins. Modulates the cellular response to ER stress in a PIK3R-dependent manner. Binds to the cis-acting X box present in the promoter regions of major histocompatibility complex class II genes. Involved in VEGF-induced endothelial cell (EC) proliferation and retinal blood vessel formation during embryonic development but also for angiogenesis in adult tissues under ischemic conditions. Also functions as a major regulator of the UPR in obesity-induced insulin resistance and type 2 diabetes for the management of obesity and diabetes prevention (By similarity). [Isoform 1]: Plays a role in the unconventional cytoplasmic splicing processing of its own mRNA triggered by the endoplasmic reticulum (ER) transmembrane endoribonuclease ERN1: upon ER stress, the emerging XBP1 polypeptide chain, as part of a mRNA-ribosome-nascent chain (R-RNC) complex, cotranslationally recruits its own unprocessed mRNA through transient docking to the ER membrane and translational pausing, therefore facilitating efficient IRE1-mediated XBP1 mRNA isoform 2 production. In endothelial cells (EC), associated with KDR, promotes IRE1-mediated XBP1 mRNA isoform 2 productions in a vascular endothelial growth factor (VEGF)- dependent manner, leading to EC proliferation and angiogenesis. Functions as a negative feed-back regulator of the potent transcription factor XBP1 isoform 2 protein levels through proteasome-mediated degradation, thus preventing the constitutive activation of the ER stress response signaling pathway. Inhibits the transactivation activity of XBP1 isoform 2 in myeloma cells (By similarity). Acts as a weak transcriptional factor. Together with HDAC3, contributes to the activation of NFE2L2-mediated HMOX1 transcription factor gene expression in a PI(3)K/mTORC2/Akt-dependent signaling pathway leading to EC survival under disturbed flow/oxidative stress. Binds to the ER stress response element (ERSE) upon ER stress. Binds to the consensus 5'-GATGACGTG[TG]N(3)[AT]T-3' sequence related to cAMP responsive element (CRE)-like sequences. Binds the Tax-responsive element (TRE) present in the long terminal repeat (LTR) of T-cell leukemia virus type 1 (HTLV-I) and to the TPA response elements (TRE). Associates preferentially to the HDAC3 gene promoter region in a static flow-dependent manner. Binds to the CDH5/VE-cadherin gene promoter region. [Isoform 2]: Functions as a stress-inducible potent transcriptional activator during endoplasmic reticulum (ER) stress by inducing unfolded protein response (UPR) target genes via binding to the UPR element (UPRE). Up-regulates target genes encoding ER chaperones and ER-associated degradation (ERAD) components to enhance the capacity of productive folding and degradation mechanism, respectively, in order to maintain the homeostasis of the ER under ER stress. Plays a role in the production of immunoglobulins and interleukin-6 in the presence of stimuli required for plasma cell differentiation (By similarity). Induces phospholipid biosynthesis and ER expansion. Contributes to the VEGF-induced endothelial cell (EC) growth and proliferation in a Akt/GSK-dependent and/or -independent signaling pathway, respectively, leading to beta-catenin nuclear translocation and E2F2 gene expression. Promotes umbilical vein EC apoptosis and atherosclerotisis development in a caspase-dependent signaling pathway, and contributes to VEGF-induced EC proliferation and angiogenesis in adult tissues under ischemic conditions. Involved in the regulation of endostatin-induced autophagy in EC through BECN1 transcriptional activation. Plays a role as an oncogene by promoting tumor progression: stimulates zinc finger protein SNAI1 transcription to induce epithelial-to-mesenchymal (EMT) transition, cell migration and invasion of breast cancer cells. Involved in adipocyte differentiation by regulating lipogenic gene expression during lactation. Plays a role in the survival of both dopaminergic neurons of the substantia nigra pars compacta (SNpc), by maintaining protein homeostasis and of myeloma cells. Increases insulin sensitivity in the liver as a response to a high carbohydrate diet, resulting in improved glucose tolerance. Also improves glucose homeostasis in an ER stress- and/or insulin-independent manner through both binding and proteasome-induced degradation of the transcription factor FOXO1, hence resulting in suppression of gluconeogenic genes expression and in a reduction of blood glucose levels. Controls the induction of de novo fatty acid synthesis in hepatocytes by regulating the expression of a subset of lipogenic genes in an ER stress- and UPR-independent manner (By similarity). Associates preferentially to the HDAC3 gene promoter region in a disturbed flow-dependent manner. Binds to the BECN1 gene promoter region. Binds to the CDH5/VE-cadherin gene promoter region. Binds to the ER stress response element (ERSE) upon ER stress. Binds to the 5'-CCACG-3' motif in the PPARG promoter (By similarity). Binds to the HEPN1 gene promoter region and activates transcription.
Synonyms: XBP-1; TREB-5; TREB5; XBP2
Tractability: Small molecule: a high-quality ligand is known; it belongs to a druggable protein family. Antibody: UniProt places it where antibodies can reach, with medium confidence; UniProt predicts a signal peptide or a membrane-spanning region. PROTAC: UniProt records ubiquitination sites on it; ubiquitination databases record sites on it; a small molecule that binds it is known.
Target class: Transcription factor
Safety:
Unwanted effects reported when the protein is acted on. In parentheses: how it was acted on, where the effect was seen, and who reports it.
be responders to treatment (source: ClinPGx)
nausea or vomiting (source: ClinPGx)
No significant findings (source: ClinPGx)
Gene: Protein-coding gene on chromosome 22 (28,794,555 to 28,800,597, reverse strand). Ensembl gene ENSG00000100219.
Subcellular location: Endoplasmic reticulum; Nucleus (Isoform 1); Cytoplasm; Endoplasmic reticulum membrane; Membrane; Nucleus (Isoform 2); Cytoplasm (X-box-binding protein 1, cytoplasmic form); Nucleus
Pathways (Reactome):
Cellular responses to stimuli: ATF6 (ATF6-alpha) activates chaperone genes; IRE1alpha activates chaperones; XBP1(S) activates chaperone genes
Gene Ontology:
Molecular function: cis-regulatory region sequence-specific DNA binding; DNA-binding transcription factor activity; identical protein binding; protein binding; protein heterodimerization activity; sequence-specific double-stranded DNA binding; DNA-binding transcription factor activity, RNA polymerase II-specific; RNA polymerase II cis-regulatory region sequence-specific DNA binding; RNA polymerase II transcription regulatory region sequence-specific DNA binding; sequence-specific DNA binding
Biological process: cellular response to lipopolysaccharide; endoplasmic reticulum unfolded protein response; negative regulation of endoplasmic reticulum stress-induced intrinsic apoptotic signaling pathway; positive regulation of angiogenesis; positive regulation of B cell differentiation; positive regulation of cell migration; positive regulation of cell population proliferation; positive regulation of immunoglobulin production; positive regulation of MHC class II biosynthetic process; positive regulation of plasma cell differentiation; positive regulation of T cell differentiation; positive regulation of transcription by RNA polymerase II; positive regulation of vascular wound healing; adipose tissue development; angiogenesis; ATF6-mediated unfolded protein response; cellular response to amino acid stimulus; cellular response to fructose stimulus; cellular response to glucose starvation; cellular response to glucose stimulus; cellular response to insulin stimulus; cellular response to interleukin-4; cellular response to nutrient; cellular response to peptide hormone stimulus; cholesterol homeostasis; and 21 more
Cellular component: cytoplasm; endoplasmic reticulum; endoplasmic reticulum membrane; membrane; nucleus; RNA polymerase II transcription regulator complex; nucleoplasm
Genetic constraint (gnomAD): Loss-of-function variants: 18 observed, 34.29 expected, observed/expected ratio (o/e) 0.52, 90% interval 0.36 to 0.78. The upper end of that interval is the gene's LOEUF score, 0.78, which puts it in group 3 of 6, group 1 being the genes least tolerant of losing a copy. Missense variants: 422 observed, 437.14 expected, observed/expected ratio (o/e) 0.97, 90% interval 0.89 to 1.05. Synonymous variants: 191 observed, 180.78 expected, observed/expected ratio (o/e) 1.06, 90% interval 0.94 to 1.19.
Homologues: Orthologues: chimpanzee XBP1 (99% identical), macaque XBP1 (98% identical), dog XBP1 (89% identical), pig XBP1 (87% identical), mouse Xbp1 (85% identical), rat Xbp1 (84% identical), zebrafish xbp1 (29% identical).
Diseases named in the same sentence as XBP1 in open-access papers:
XBP1 is named in the same sentence as 330 diseases in open-access papers, as found by Europe PMC text mining. Sharing a sentence is not in itself a finding about the gene and the disease. The quoted sentences say what the papers report.
breast carcinoma (135 papers, 2007 to 2026). "The GWAS risk allele associated with breast cancer leads to an increased XBP1 expression, while the opposite effect is observed for the GWAS risk alleles associated with ovarian cancer." (PMID 39623312, 2024). "Using the IVW method, we identified a genetic causal effect of XBP1 on three diseases other than AF and breast cancer." (PMID 39170695, 2024). "Several studies have confirmed the close association between XBP1 and breast cancer, especially ER-positive breast cancer, which is consistent with our findings." (PMID 39170695, 2024). "The top eQTL for XBP1 represents a GWAS risk variant for breast cancer upon TBOOH treatment (r2 = 0.802) and for ovarian cancer upon TBOOH treatment (r2 = 0.73) and HC treatment (r2 = 0.746)." (PMID 39623312, 2024). "One study identified five non-coding regulatory elements of XBP1 in breast cancer cells, which are the hotspots of breast cancer mutations." (PMID 39544254, 2024). "Multiple lines of evidence have proved that the HIF1α pathway is vital for glioma angiogenesis, and sensors associated with IRE1α and XBP1 have been reported to be involved in the regulation of HIF1α pathway in breast cancer." (PMID 36997943, 2023). "Further, XBP1-gene signature was associated with poor RFS among different cohorts of breast cancer patients." (PMID 36997866, 2023). "XBP1 expression is associated with the prognosis of several cancers, including breast cancer and lung adenocarcinoma." (PMID 36496988, 2022). "By using small interfering RNA (siRNA)-based therapeutics, our recent work demonstrated X-box-binding protein 1 (XBP1) was linked to human epidermal growth factor receptor 2 positive (HER2+) breast cancer development and chemoresistance." (PMID 33413427, 2021). "We recently demonstrated that ERα-associated networks differ between endometrial and breast cancer and that these networks have distinct regulators, with a unique role for XBP1 (X-box binding protein 1) in endometrial cancer." (PMID 32069845, 2020). "Data mining using the Catalogue of Somatic Mutations in Cancer (COSMIC) platform revealed that IRE1 and XBP1 are rarely mutated in breast cancer (0.47% and 0.67%, respectively)." (PMID 30248920, 2018). "The overexpression and splicing of XBP1 have been associated with poor outcomes in breast cancer patients." (PMID 26459317, 2015). "For instance, Davies and colleagues have linked low levels of unspliced XBP1 as well as a high spliced/unspliced XBP1 ratio with poor disease outcome in 100 primary breast carcinoma patients treated with adjuvant hormonal therapy." (PMID 26300886, 2015). "It is reported that XBP1 is over expressed in aggressive breast cancer and associated with cancer cell survival and therapy resistance." (PMID 22681620, 2012). "Gene expression profiling of ex-vivo breast cancer tissue has previously shown an association between ER expression and XBP-1 expression." (PMID 19861963, 2009). "This study is the first to show an association between both GRP78 and XBP-1 with increasing ER positivity in clinical breast cancer samples." (PMID 19861963, 2009). "XBP1 was analyzed using C-map, which suggested the presence of 202 drugs that inhibit XBP1 expression (score:|>90|) with a similar effect as knockdown of the gene, which could reduce the risk of AF and breast cancer (total, ER+)." (PMID 39170695, 2024). "In addition, unspliced XBP1 is associated with longer survival of breast cancer patients treated with tamoxifen, which is opposite to XBP1 splicing that is associated with shorter survival." (PMID 32138264, 2020). "Human X -box binding protein 1 (XBP1), a critical gene in the endoplasmic reticulum stress response, is located on chromosome 22q12, which has been linked with the pathogenesis of many diseases, particularly cancers such as breast cancer (BC)." (PMID 31554371, 2019). "XBP1 is highly expressed in luminal breast cancers but it is rarely found to be mutated." (PMID 30248920, 2018).
breast carcinoma (continued). "In addition, xenograft mice transfected with MDA-MB-231 breast cancer cells with an shRNA targeting XBP1, reduces the risk of breast cancer tumor relapse." (PMID 26622781, 2015). "XBP1 forms a strong homodimer (Kd = 8 nM), is important for regulating the unfolded protein response and plasma cell differentiation, and has been implicated as an important gene contributing to breast cancer progression." (PMID 25695764, 2015). "For these reasons, XBP-1(S) may be considered an important diagnostic and prognostic biomarker of breast cancer samples and may be also a useful tool in the identification of ER-positive breast tumors with a relatively poor response." (PMID 23192763, 2013). "In addition, XBP1 deficiency inhibits the proliferation of breast cancer cells." (PMID 38517922, 2024). "In addition, we identified XBP1 as a druggable gene that reduces the risk of AF and breast cancer, and treatment against this target may also reduce other diseases." (PMID 39170695, 2024). "Thus, IRE1/XBP1 signaling is intimately linked to ESR1 signaling in luminal breast cancer." (PMID 30248920, 2018). "While hsa-miR-3184-5p has not yet been linked to endometriosis, it exerts tumor-suppressive effects in ovarian and breast cancers via modulation of XBP1/AKT/STAT3, FOXP4, and EMT-related signalling." (PMID 41501788, 2026). "XBP1 induces cell invasion and metastasis in breast cancer cells, with high expression promoting tumor cell proliferation." (PMID 39954675, 2025). "In the IRE1α–X-box binding protein 1 (XBP1) axis, knockdown of XBP1 has been shown to inhibit the growth of estrogen receptor 1 (ESR1)-positive breast cancer cells, demonstrating its pro-survival role in hormone-responsive tumors." (PMID 40564269, 2025). "For instance, glucose restriction has been shown to induce XBP1 splicing and activation in primary breast cancer models, highlighting its central role in metabolic stress adaptation." (PMID 41209558, 2025). "ORIN1001 is a notable IRE1α-XBP1 blocker that is currently progressing in phase II clinical trials for advanced solid tumors (recruiting for advanced breast cancer patients)." (PMID 41301006, 2025). "Elevated spliced form of X‐box–binding protein 1 (XBP1) correlates with unfavorable responses to endocrine therapy plus CDK4/6 inhibitors in HR+/HER2− advanced breast cancer." (PMID 40940685, 2025). "In breast cancer, the hormonal therapy drug fulvestrant indirectly inhibits the IRE1α-XBP1 axis, resulting in selective apoptosis." (PMID 41301006, 2025). "Evidence suggests that inhibition of IRE1 (Rnase site) leads to decreased splicing of XBP1, which reduces cell proliferation and increases apoptosis in breast cancer, pancreatic cancer, and multiple myeloma." (PMID 40976979, 2025). "Downregulation of XBP1 using XBP1siRNA decreased angiogenesis, hindered cell proliferation, and inhibited breast cancer growth by improving sensitization of chemotherapy." (PMID 39199788, 2024). "Numerous studies have shown that the UPR can promote the proliferation of tumors such as liver cancer, melanoma, and breast cancer through various signaling cascades such as IRE1/XBP1/JNK, IRE1/XBP1/IL-6/STAT3, and IRE1/TRAF2/NF-κB." (PMID 39080273, 2024). "Systemic delivery of aptamer-conjugated XBP1siRNA, 3WJ-HER2apt-siXBP1 NPs exhibited efficient XBP1 silencing, resulting in breast cancer suppression." (PMID 39199788, 2024). "Conversely, the inhibition of IRE1α and the subsequent reduction in spliced Xbp1 protein increased mortality in anti-estrogen treatment for breast cancer cells." (PMID 39768160, 2024). "Further experimental results show that XBP1 is upregulated in human HER2-positive breast cancer, and its knockdown significantly inhibited cell proliferation." (PMID 39006091, 2024). "In a study, immunohistochemical staining of tissues from 395 human BCs revealed that Bip and XBP-1 were expressed in 76% and 90% of breast cancers, respectively." (PMID 38509524, 2024).